INS (insulin)
Diseases named in the same sentence as INS in open-access papers (continued):
Sharing a sentence is not in itself a finding about the gene and the disease.
Hyperglycemia (continued). "According to the patient’s hyperglycemia, he received a low-carbohydrate diet, once-daily insulin degludec injection(long-acting insulin, 14 U) before sleep, glimepiride 2 mg per day and acarbose 50 mg with every meal." (PMID 38036957, 2023). "The sustained hyperglycemia, high-level serum insulin and insulin-like growth factor were regarded as possible mechanisms for carcinogenesis in diabetic patients." (PMID 36932111, 2023). "In contrast, the administration of monoclonal antibodies that neutralize serum MG53 protein has been shown to improve hyperglycemia and increase insulin sensitivity in diabetic mice." (PMID 37699054, 2023). "IR is a metabolic disorder characterized by the body's reduced ability to respond to insulin, leading to hyperglycemia and impaired glucose metabolism." (PMID 37667704, 2023). "Previous studies have revealed that the short-term effects of WP supplementation were equivalent to insulin therapy or sulfonylurea for the treatment of hyperglycemia in T2DM patients." (PMID 37798798, 2023). "Mice lacking Hmgcr in β-cells exhibited low insulin concentrations and hyperglycemia attributable to decreases in both β-cell mass and insulin secretion." (PMID 37795366, 2023). "In this model, STZ is used to injure pancreatic β islet cells, leading to reduced insulin secretion and sustained hyperglycemia and secondary injury of the retinal microvasculature." (PMID 37227777, 2023). "Although its use in T2DM is unusual for newly diagnosed patients, there are several instances in which the use of insulin is considered, such as severe hyperglycemia, gestational diabetes, the presence of significant weight loss and ketonuria." (PMID 37298274, 2023). "As expected, stress-induced hyperglycaemia with a decrease in the insulin signaling pathway and altered gene expression in glycolysis and gluconeogenesis, suggesting the disturbance of glycometabolism." (PMID 36814911, 2023). "We aimed to develop a novel model for simulating T2D in vitro, including hyperglycemia, hyperlipidemia, and variably elevated insulin levels targeting muscle cells." (PMID 38132105, 2023). "The management of CFRD has traditionally been centered on correcting hyperglycemia through administering insulin combined with dietary modifications and physiotherapy." (PMID 37893045, 2023). "Accordingly, STZ led to reduced fasting insulin levels in LinSTZ mice, confirming beta cells injury-mediated hyperglycemia." (PMID 36730247, 2023). "In STZ mice O304 reduced hyperglycemia by stimulating insulin independent glucose uptake and utilization in skeletal muscle, i.e., stimulated glucose effectiveness." (PMID 37626210, 2023). "Neonatal diabetes mellitus (NDM) is a rare genetic disease characterized by severe hyperglycemia requiring insulin therapy with onset mostly within the first 6 months and rarely between 6-12 months of age." (PMID 37251668, 2023). "The mice displayed liver steatosis, hyperglycemia and glucose intolerance, accompanied by hepatic insulin insensitivity and elevated serum insulin levels." (PMID 37298278, 2023). "SeNP and/or BV administration resulted in a reduction of the hyperglycemia produced by STZ administration through an improvement of insulin production." (PMID 36984840, 2023). "As people age, the glucose sensitivity of pancreatic cells decline and insulin secretion is impaired, leading to hyperglycemia and T2DM." (PMID 37501094, 2023). "Hyperglycemia-related mortality following injection of high doses of STZ can be overcome with insulin administration." (PMID 36998708, 2023). "Only one patient had hyperglycemia that needed treatment with insulin and was detected via the CGMS." (PMID 37761385, 2023). "If hyperglycemia is identified, an additional dose of injectable insulin will be required in the following HD therapy." (PMID 37445782, 2023).
Hyperglycemia (continued). "Subsequently, Chen’s group found that the oral administration of aglycin in diabetic mice effectively controlled hyperglycemia by improving the insulin-signaling pathway and enhancing glucose uptake in peripheral tissues." (PMID 36904097, 2023). "On glucose tolerance testing, hyperglycaemia occurred at 60 min (glucose 216 mg/dL) and hypoglycaemia at 300 min (52 mg/dL) concurrent with an apparent plasma insulin concentration of 52 850 pmol/L on immunoassay." (PMID 37818852, 2023). "DM is a group of physiological dysfunctions characterized by hyperglycemia resulting directly from insulin resistance, inadequate insulin secretion, or excessive glucagon secretion." (PMID 37377963, 2023). "Diabetic rats treated with insulin appear to protect hyperglycemia-induced trabecular bone deterioration." (PMID 36674494, 2023). "It is thought that hyperglycemia caused by uncontrolled FOXO1 activation, combined with chronic hyperinsulinemia, can remove insulin’s inhibitory effect on lipolysis in adipose tissue." (PMID 36902173, 2023). "Chronic hyperglycaemia impairs both insulin sensitivity and pancreatic insulin secretion, initiating a vicious cycle that gradually increases insulin resistance and deteriorates β-cell function." (PMID 37568149, 2023). "A study with an experimental diabetic rat model showed that oral chromium picolinate administration attenuated hyperglycemia-induced oxidative stress and probably enhanced insulin production by β-cells." (PMID 37432389, 2023). "Body's resistance to insulin is one of the important factors contribute to the hyperglycemia intype-2 diabetes." (PMID 37822828, 2023). "Type I diabetes Mellitus (T1DM) is an autoimmune disorder targeting the destruction of pancreatic insulin-producing beta cells, ultimately leading to hyperglycemia and the requirement of insulin therapy for survival." (PMID 36875761, 2023). "The subjects were critically ill children with cardiopulmonary failure who were a part of a prospective randomized insulin titration trial to treat hyperglycemia." (PMID 37693502, 2023). "Vesicles were loaded into a MN-array patch and disassembled in case of interstitial hyperglycaemia with insulin delivery." (PMID 37685946, 2023). "French and international guidelines recommend monitoring the blood glucose level every 2 h in critically ill patients and to address hyperglycaemia with continuous intravenous (IV) insulin infusion." (PMID 37330419, 2023). "This is because in patients with uncontrolled hyperglycemia, “stunned” β-cells lead to an impairment in insulin secretion." (PMID 37102024, 2023). "Reduced glucose tolerance and insulin sensitivity.Hyperglycemia and hyperinsulinemia at both fasting and fed states." (PMID 38317714, 2023). "In an animal model of stroke, hyperglycemia accelerates symptoms of cellular acidosis in the ischemic penumbra, resulting in larger infarct size than in hypoglycemic animals treated with insulin." (PMID 36914967, 2023). "Conversely, inhibition of beta-cell mass expansion in Tam-injected βNrf2KO mice led to reduced plasma insulin levels, decreased glucose tolerance and hyperglycemia." (PMID 37693560, 2023). "From a glucose perspective, insulin therapy in T2DM is therefore aimed at preventing excessive gluconeogenesis, that is, fasting hyperglycaemia with basal insulin and short (or ultra-short) acting insulin to limit the degree of postprandial glucose increases." (PMID 37132569, 2023). "Metformin was used as a positive control to prevent hyperglycemia, hyperinsulinemia, and hypertension through its insulin-sensitizing effect." (PMID 36829899, 2023). "Hyperglycemia was dramatically reduced in the groups treated with okra and insulin compared to the diabetic group." (PMID 38046568, 2023). "Altogether these findings show that in diabetic STZ mice, O304 ameliorated hyperglycemia by stimulating insulin independent glucose uptake and utilization, mitigated glycogen accumulation, and reverted diabetic cardiomyopathy." (PMID 37626210, 2023).
Hyperglycemia (continued). "Chronic adipsin supplementation in db/db mice ameliorated hyperglycemia, increased insulin levels, and preserved beta cells." (PMID 37761031, 2023). "Only the rate of hyperglycemia requiring insulin infusion was significantly higher in the AI group than in the non-AI group (OR = 14.15, 95% CI = 1.44–138.60, p = 0.02)." (PMID 36676776, 2023). "NAFLD is accompanied by impaired insulin-mediated suppression of hepatic glucose production, leading to liver steatosis, hyperglycemia and dyslipidemia." (PMID 37794971, 2023). "HFD mice also showed hyperglycaemia and altered glucose and insulin sensitivity compared to the lean mice, confirming that ten weeks of a hyperlipidemic diet are enough to affect metabolic homeostasis." (PMID 38067134, 2023). "Reported insulin-mimicking and insulin-releasing actions, insulin secretion, glucose uptake, and suppression of peripheral glucose release in hyperglycemia have been found in TC’s isoquinoline alkaloids, including palmatine, jatrorrhizine, and magnoflorine." (PMID 37242122, 2023). "Various studies have evaluated the safety and efficacy of using insulin pumpsduring Ramadan; some of them demonstrated favorable outcomes in reducinghypoglycemia and hyperglycemia." (PMID 34809475, 2023). "On the other hand, whole grains due to their high fiber content, cause slow absorption of carbohydrates in the gastrointestinal tract and decrease glycemic index, which ultimately reduces the rate of hyperglycemia and blood insulin." (PMID 37076804, 2023). "As a result, a food pattern with a high GL is likely to lead to mental disorders and sleep disorders through hyperglycemia, increasing basal insulin, and creating a steep insulin peak." (PMID 36750913, 2023). "The physiological changes in the elderly, characterized by insufficient insulin secretion, changes in body composition, and increased insulin resistance due to age-related sarcopenia, would increase the blood glucose level (hyperglycemia)." (PMID 37305528, 2023). "After stroke, glucocorticoids and inflammatory mediators induce insulin resistance and hyperglycaemia." (PMID 37438755, 2023). "Under diabetic conditions, when pancreatic β-cells are chronically exposed to hyperglycemia, β-cells are compelled to continuously secrete larger amounts of insulin to reduce blood glucose levels." (PMID 37720599, 2023). "Animal models demonstrated that fetal and neonatal skeletal muscles were insulin resistant after only 2-day continuous intrauterine hyperglycemia." (PMID 37255932, 2023). "A decrease in insulin production by beta islet cells and the impairment of insulin receptors are among the factors that lead to hyperglycaemia." (PMID 36372924, 2023). "During the management of patients in acute trauma the resulting transient hyperglycemia is treated by administration of insulin." (PMID 37998031, 2023). "In both groups, insulin levels increase at the early stages of T2D onset following the hyperglycemia." (PMID 38026205, 2023). "Two previous studies, carried out in subjects with cystic fibrosis-related diabetes and in a lipopolysaccharide-induced septic rat model, respectively, have shown that HMGB1 was increased in the presence of hyperglycaemia and was lowered after insulin therapy." (PMID 37256493, 2023). "Globally, diabetic mellitus (DM) is a common metabolic disease that effectively inhibits insulin production, destroys pancreatic β cells, and consequently, promotes hyperglycemia." (PMID 37111630, 2023). "It is increasingly understood that glucose metabolism is regulated by redox homeostasis, where the redox imbalance contributes to insulin resistance and hyperglycemia development." (PMID 37337262, 2023). "In the meantime, STZ induced hyperglycemia suppressed the insulin mRNA expression and boosted the glucagon mRNA expression." (PMID 37520251, 2023).
Hyperglycemia (continued). "Diabetes is a chronic metabolic disease characterized by insufficiency in insulin secretion from pancreatic β-cells, which leads to the accumulation of glucose in plasma and eventually to hyperglycemia." (PMID 36902160, 2023). "In keeping with this, it is highly likely that improved function of beta‐cells (and hence insulin secretion) will delay the onset of hyperglycemia and reduce complications." (PMID 37522521, 2023). "We found hyperglycemia-induced persistent ROS generation and TGase activation after blood glucose normalization in the retina, lung, and kidney of insulin-supplemented diabetic mice." (PMID 36782199, 2023). "Nevertheless, studies have shown that GPLD1 serum level can be regulated by various factors such as insulin serum level, hyperglycemia, ROS and inflammation." (PMID 37151681, 2023). "IR is a condition that is characterized by the failure of insulin to provide the proper glucose transport into the tissues, which results in the development of hyperglycemia and hyperinsulinemia." (PMID 37626790, 2023). "In detail, although ablating PERK is shown to impair insulin trafficking and β cell survival, leading to insulin insufficiency and hyperglycemia, partial attenuation of PERK activity instead enhances GSIS through regulating ER chaperones and Ca2+ transit." (PMID 37303813, 2023). "The insulin level in HHS is low enough to induce extracellular hyperglycemia by decreasing tissue utilization and stimulating the release of glucagon and other counter-regulatory stress hormones to initiate glycogenolysis and gluconeogenesis (like DKA)." (PMID 38002864, 2023). "As the disease progresses, insulin secretion is unable to maintain glucose homeostasis, resulting in hyperglycemia." (PMID 37764820, 2023). "In fact, patients with RFX6-MODY had normal development of the β islet cells but defective insulin secretion, leading to hyperglycemia." (PMID 38162681, 2023). "Glycogenic hepatopathy typically occurs in children and adults with marked or prolonged hyperglycemia, followed by exogenous administration of insulin in the setting of type 1 DM." (PMID 37047105, 2023). "Women with GDM produce more insulin than healthy pregnant women, maternal hyperglycemia stimulates fetal pancreatic beta cells to produce more insulin, which can lead to increased fetal nutrient uptake and growth." (PMID 37529595, 2023). "Hesperetin is effective in mitigating hyperglycemia by potentially promoting the release of insulin from the beta cells within the islets." (PMID 37943820, 2023). "The underlying molecular metabolism that PN exerted beneficial effects on hyperglycemia, insulin sensitivity, and NAFLD progression was demonstrated in this study." (PMID 37426418, 2023). "This, in turn, leads to further down-regulation of on-cell membranes in insulin-dependent tissues, followed by reduced glucose uptake by these tissues and subsequent hyperglycemia." (PMID 37445466, 2023). "In the diabetic patient with hyperglycemia, the frequency of glucose generation increases, and at the same time, serum insulin levels increase, indicating the presence of insulin resistance in both organs." (PMID 37675359, 2023). "The daily glycemic profile was assessed by CGM sensor tracing and we found that vildagliptin as an add-on to insulin delivered by AHCL mainly improved postprandial hyperglycemia, although pre-iftar blood glucose levels were similar in both groups." (PMID 38057844, 2023). "The observed hyperglycemia results from a combination of reduced insulin‐mediated glycolysis and of glycogenolysis early in the anesthetic and surgical procedure." (PMID 36808704, 2023). "Guava-leaf extract supplementation reduced hyperglycemia, enhanced glucose tolerance and insulin sensitivity, and decreased inflammatory cell infiltration and fibrosis." (PMID 37761200, 2023).
Hyperglycemia (continued). "In thefuture, we should emphasize the occurrence of stress hyperglycemia and glucosemanagement, preferably with insulin, when treating patients with acutemyocarditis." (PMID 39076259, 2023). "Blackberry juice protected pancreatic beta cells from necrosis and apoptosis by decreasing lipid peroxide activity, enhancing catalase activity leading to a progressive recovery of insulin output, and improved management of hyperglycemia." (PMID 37280499, 2023). "All PI3K inhibitors induce a disruption in the carbohydrate metabolism with hyperglycemia; hyperglycemia brings feedback that leads to insulin upregulation and reactivation of tyrosine kinase receptors (RTKs)." (PMID 36900211, 2023). "Collectively, RT exhibits the greatest improvements in this biomarker, helping to reduce hyperglycemia and glycosylated hemoglobin, and improving peripheral insulin sensitivity." (PMID 36833129, 2023). "Although the patient had episodes of hyperglycemia (somatostatin can inhibit both glucagon and insulin secretion), postprandial hyperinsulinemic hypoglycemia was also detected and related to postmortem findings of islet cell hyperplasia." (PMID 37371827, 2023). "From a clinical standpoint, insulin therapy has to be tailored in women experiencing premenstrual hyperglycaemia." (PMID 36836608, 2023). "When brain tissue passes into a state of insulin resistance, hyperglycemia arises, a condition characteristic of DM type-2." (PMID 36834741, 2023). "Stress hyperglycaemia is a common condition in patients with any acute illness when the interaction of various cytokines and stress hormones leads to a state of insulin resistance and increased glucose production." (PMID 38255162, 2023). "T2DM is a chronic condition characterized by hyperglycemia due to inadequate insulin secretion and/or defective insulin action." (PMID 37664847, 2023). "Vildagliptin 50 mg QD has proven safety and efficacy in severe renal impairment when hyperglycemia is uncontrolled with insulin and in patients on dialysis." (PMID 37378205, 2023). "DM is a group of metabolic diseases characterized by hyperglycemia, resulting from defects in insulin secretion or response to insulin." (PMID 36902521, 2023). "Here we first demonstrate that functional ablation of Pitpna in murine beta-cells results in random-fed hyperglycemia due to both impaired glucose-stimulated insulin secretion (GSIS) and reduced beta-cell number." (PMID 37460527, 2023). "It is commonly believed that under healthy conditions, hyperglycemia induces insulin production to promote glycogen storage in the liver, skeletal muscle, and fat cells." (PMID 37948457, 2023). "Although ROS are intracellular signals necessary for some physiological processes, their accumulation leads to oxidative stress, hyperglycemia, and progressive resistance to insulin." (PMID 37298303, 2023). "Fasting hyperglycaemia occurs as a result of diurnal changes in cortisol and growth hormone secretion and increased hepatic glucose production and reduced hepatic insulin sensitivity amplified in pregnancy." (PMID 36904224, 2023). "GLP1 is a hormone which can reduce the glucagon:insulin ratio and is higher in female mice, a model of protection from olanzapine-induced hyperglycemia, compared to male or ovariectomized mice." (PMID 36937886, 2023). "Subsequent surgical stresses led to hyperglycemia and eventual recovery of insulin secretion and normalized insulin‐to‐glucose ratios in later stages of the procedure and in recovery." (PMID 36808704, 2023). "Nevertheless, during labour and delivery, they experienced hyperglycemia when insulin management was done by the healthcare team." (PMID 37131168, 2023). "In this review, a recently published rat DM model induced by streptozotocin injection with chronic exogenous administration of insulin to reduce hyperglycaemia has also been included in an attempt to mimic the chronic phase of DM in humans." (PMID 37373455, 2023).